RASGRP1 (RAS guanyl releasing protein 1)
Diseases named in the same sentence as RASGRP1 in open-access papers (continued):
Sharing a sentence is not in itself a finding about the gene and the disease.
B cell lymphoma (5 papers, 2018 to 2023). "It is important to note that some patients with loss-of-function RasGRP1 mutants develop Epstein–Barr virus (EBV)-induced B cell lymphoma." (PMID 36675167, 2023). "Like CD27‐, CD70‐deficient patients, RASGRP1‐deficient patients appear to be particularly prone to develop EBV‐driven B‐cell lymphoma as the four patients described today had Hodgkin lymphoma." (PMID 29282224, 2018). "DAG and its analogues have long been known to activate RasGRP1 in T and B cells, and the treatment of B cell lymphoma-derived cell lines with DAG analogues promoted apoptosis." (PMID 36675167, 2023). "Particularly, in B-cell lymphomas and T-cell leukemias, RASGRP1 and CRAF, two HSP90 client proteins, are degraded upon HDAC6 inhibition, leading to RASGRP1/CRAF-dependent apoptosis." (PMID 36765939, 2023). "In humans, deficiencies in RASGRP1 can result in a primary immunodeficiency (PID) syndrome, characterized by lymphopenia in CD4 + T cells and the development of Epstein-Barr virus (EBV)-associated B cell lymphoma." (PMID 38057716, 2023). "Similarly, RAS guanyl-releasing protein 1 (RASGRP1) deficiency has been involved with T-cell lymphopenia and EBV-associated B-cell lymphoma." (PMID 35603189, 2022).
breast carcinoma (5 papers, 2015 to 2025). "Specifically, it was found that the upregulation of Rasgrp1 was associated with an improved overall survival in breast cancer, as well as overall survival and disease-free survival in the triple-negative breast cancer subtype." (PMID 36675167, 2023). "High RASGRP1 expression was demonstrated to be associated with a better prognosis in breast cancer." (PMID 36467500, 2022). "Lastly, only in recent years was RasGRP1 identified as a differentially expressed gene correlated with overall and disease-free survival in breast cancer." (PMID 36675167, 2023). "A previous study showed that higher expression of RASGRP1 was related to better overall survival and disease-free survival in breast cancer." (PMID 34104083, 2021). "The role of RasGRP1 in breast cancer has only recently been studied." (PMID 36675167, 2023). "A second area is the clinical behavior of tumors relative to the expression of RasGRP1 in various cancers, such as CRC, HCC, and breast cancer." (PMID 36675167, 2023). "Furthermore, RAS guanyl nucleotide-releasing protein (RASGRP1) activates the Erk/MAP kinase cascade, regulates the development of T- and B-cells, homeostasis and differentiation, and is involved in regulation of breast cancer cells." (PMID 25888030, 2015).
hepatocellular carcinoma (5 papers, 2020 to 2024). A malignant tumor that arises from hepatocytes. "RasGRP1 has been found to be upregulated in hepatocellular carcinomas (HCC); furthermore, a high RasGRP1 expression is associated with the tumor size, tumor–node–metastasis (TNM) stage, and Barcelona Clinic Liver Cancer stage." (PMID 36675167, 2023). "At the protein level, RasGRP1 overexpression significantly inhibits the tumour-promoting effect of IL-6 in hepatocellular carcinoma progenitor cell-like spheroids." (PMID 36385095, 2022).
lymphoproliferative disorders (5 papers, 2014 to 2024). "Mice deficient in RASGRP1 may induce auto-reactive B cells disrupt immune tolerance through a T-cell mechanism, and are at increased risk of developing lymphoproliferative disorders characteristic of human SLE." (PMID 37426642, 2023). "Our study highlights the fact that RASGRP1 deficiency is a major risk factor for EBV‐driven lymphoproliferative disorders and demonstrates the critical function of RASGRP1 in pathways required for expansion of activated T cells in humans, a key step in immunity to EBV." (PMID 29282224, 2018).
rheumatoid arthritis (4 papers, 2015 to 2024). A chronic, systemic autoimmune disorder characterized by inflammation in the synovial membranes and articular surfaces. "In this study, we employed bioinformatics and machine learning techniques to identify seven key genes associated with rheumatoid arthritis (RA): AKR1B10, MMP13, FABP4, NCF1, SPP1, COL1A1, and RASGRP1." (PMID 39430588, 2024).
acute myelogenous leukemia (3 papers, 2012 to 2022). "A recent clinical trial in patients with acute myelogenous leukemia has shown that patients whose tumor cells have a high ratio of expression of two genes, RASGRP1 and APTX, are more likely to respond to R115777." (PMID 23228035, 2012). "Previous studies demonstrated that Sox4, RasGRP1, RasGRP3, IGF1R, CDK6, and LEF1 are the key oncogenes/tumor suppressor genes in acute myeloid leukemia." (PMID 31242922, 2019). "Although different translational approaches to FTI response prediction have been described, such as a two-gene classifier (RASGRP1/APTX) in patients with acute myeloid leukaemia (AML), there is still no reliable biomarker available for predicting the FTI response." (PMID 35158735, 2022).
autoimmune lymphoproliferative syndrome (3 papers, 2018 to 2023). Autoimmune lymphoproliferative syndrome (ALPS) is a rare, inherited disorder characterized by non-malignant lymphoproliferation, multilineage cytopenias, and a lifelong increased risk of Hodgkin's and non-Hodgkin's lymphoma. "These loss-of-function RasGRP1 mutants lead to the development of autoimmune lymphoproliferative syndrome (ALPS), CD4+ T cell lymphopenia, recurrent infections, hepatosplenomegaly, and lymphadenopathy." (PMID 36675167, 2023). "A recent study reported a heterozygous mutation in RASGRP1 correlated with autoimmune lymphoproliferative syndrome (ALPS)-like disease." (PMID 31164884, 2019).
melanoma (3 papers, 2021 to 2025). A malignant, usually aggressive tumor composed of atypical, neoplastic melanocytes. "The elevated levels of SAG observed in the tumors might potentiate this signaling cascade through PKC activation and enhanced RasGRP1 activation, thereby ensuring persistent and amplified MAPK/ERK pathway activation, thus promoting melanoma progression." (PMID 39934865, 2025). "On the other hand CYT-low metastatic melanomas had recurrent amplifications in loci 5p15.33 (TERT), 6p25.1 (CDYL), 7p22.2 (RAC1), 12q15 (MDM1) and recurrent deletions in 5q31.2 (CTNNA1, FGF1), 11q22.3 (FDX1, RDX, ZC3H12C), and 15q14 (RASGRP1, CSNK1A1P1, SPRED1)." (PMID 33779796, 2021).
skin tumors (3 papers, 2023 to 2025). "The presence of RasGRP1 has been confirmed in keratinocytes derived from the skin, and overexpression of this protein has been linked to the promotion of skin tumor formation, likely mediated through direct RAS activation." (PMID 39934865, 2025). "The proposed mechanism is that the act of wounding caused the release of the granulocyte colony-stimulating factor (G-CSF) by keratinocytes, and G-CSF acted in an autocrine and paracrine fashion to cooperate with RasGRP1 in the development of skin tumors." (PMID 36675167, 2023). "While studying the role of RasGRP1 in skin tumors, one group found that the overexpression of RasGRP1, driven by a K5 promotor, in keratinocytes resulted in the development of spontaneous skin tumors." (PMID 36675167, 2023).
cognitive deficits (2 papers, 2023 to 2025). "In addition, PRKCD, RASGRP1, SYNCRIP, CSNK1E, and CBX3 were involved in the regulation of synaptic plasticity and were associated with cognitive impairment caused by neurological diseases." (PMID 37106826, 2023).
colitis (2 papers, 2022 to 2025). Inflammation of the colon. "To further investigate the pathophysiological significance of these observations, we analysed the role of Rasgrp1 3’ UTR in the development of DSS-induced colitis." (PMID 36385095, 2022). "Collectively, our data suggested that the Rasgrp1 3’ UTR aggravates the development of colitis by promoting IL-6 protein production." (PMID 36385095, 2022). "In vivo overexpression of the Rasgrp1 3’ untranslated region enhances lipopolysaccharide-induced systemic inflammation and dextran sulphate sodium-induced colitis in Il6+/+ mice but not in Il6-/- mice." (PMID 36385095, 2022).
COVID-19 (2 papers, 2023). A disease caused by infection with severe acute respiratory syndrome coronavirus 2. "Based on this evidence, RASGRP1 has great potential to become a pivotal regulatory target of COVID-19 with AKI and CKD." (PMID 37026010, 2023). "DUSP6, BHLHE40, RASGRP1, and TAB2, the top 4 topological metric hub genes, appear to be pivotal molecular targets of COVID-19, AKI, and CKD." (PMID 37026010, 2023). "Hub genes identified from the protein–protein interaction (PPI) network, including DUSP6, BHLHE40, RASGRP1, and TAB2, are potential therapeutic targets in COVID-19 with AKI and CKD." (PMID 37026010, 2023). "The area under the curve (AUC) values for 6 shared hub genes (CDC6, PLCG1, KIF15, LCK, CDC25C, and RASGRP1) in the SLE dataset to discriminate between patients and healthy controls were greater than 0.61, while those for the COVID-19 dataset were greater than 0.91." (PMID 37426642, 2023).
Crohn disease (2 papers, 2016 to 2025). A gastrointestinal disorder characterized by chronic inflammation involving all layers of the intestinal wall, noncaseating granulomas affecting the intestinal wall and regional lymph nodes, and transmural fibrosis. "Seven shared risk genes (CD40, PTPN22, CD226, BATF, PRKCB, RasGRP1, and PTPN2) are involved in cytokine pathways linked to Crohn’s disease." (PMID 40839671, 2025).
Graves disease (2 papers, 2011 to 2013). Graves' disease is an autoimmune disorder that leads to overactivity of the thyroid gland (hyperthyroidism).It is caused by an abnormal immune system response that causes the thyroid gland to produce too much thyroid hormones. "Common tag SNVs near RASGRP1 are associated with susceptibility to autoimmune (Type 1) diabetes and to thyroid autoantibodies in Graves’ disease, while 13 unstudied RASGRP1 missense SNVs are currently listed in public databases." (PMID 24336796, 2013). "TPOA are commonly detected in Graves' disease patients and, therefore, the TPOA- associated SNPs located in the genes RASGRP1, UBASH3A and BACH2 that have not been previously tested for Graves' disease association are strong Graves' disease candidates." (PMID 21829393, 2011).
Hodgkins lymphoma (2 papers, 2018). A heterogeneous group of malignant lymphoid neoplasms of B-cell origin characterized histologically by the presence of Hodgkin and Reed-Sternberg (HRS) cells in the vast majority of cases. "A deleterious homozygous mutation in RASGRP1 leading to the loss RASGRP1 expression was identified in two siblings who both developed a persistent EBV infection leading to Hodgkin lymphoma." (PMID 29282224, 2018). "More recently, null homozygous mutations in RASGRP1 were reported in two patients with combined immunodeficiency associated with pulmonary infections and persistent EBV infection including EBV‐driven Hodgkin lymphoma." (PMID 29282224, 2018). "Two siblings with severe persistent EBV infection leading to EBV‐driven Hodgkin lymphoma were identified and found to be carrier of a homozygous deleterious mutation in RASGRP1, leading to the lack of RASGRP1 expression." (PMID 29282224, 2018).
liver cancer (2 papers, 2022 to 2023). An epithelial or non-epithelial malignant neoplasm that arises from the liver. "In summary, our study demonstrated that RasGRP1 is an essential regulator that promotes the inflammatory response by increasing IL-6 production and suppressing liver cancer cell growth via inhibition of EGFR-SOS1-Ras-AKT signalling pathway activation." (PMID 36385095, 2022). "Next, we evaluated the specificity of the anti-RasGRP1 antibodies and performed IHC staining for RasGRP1 in a human liver cancer tissue microarray." (PMID 36385095, 2022). "Taken together, our results indicated that the RasGRP1 protein can inhibit liver cancer by limiting EGFR-SOS1-Ras-AKT signalling." (PMID 36385095, 2022). "We found that overexpression of RasGRP1 suppressed liver cancer cell growth by inhibiting proliferative EGFR-SOS1-Ras-AKT signalling." (PMID 36385095, 2022). "However, 50% of the liver cancer tissue samples showed upregulated RasGRP1 expression compared to that in matched adjacent liver tissues." (PMID 36385095, 2022). "The liver cancer patients with upregulated RasGRP1 expression exhibited significantly smaller tumour sizes, lower γ-glutamyl transferase levels and longer total survival than the liver cancer patients with downregulated RasGRP1 expression." (PMID 36385095, 2022). "Interestingly, only 22.2% of the liver cancer tissue samples exhibited high RasGRP1 expression, with a greater percentage of samples showing moderate and low RasGRP1 expression (40% and 37.8%, respectively)." (PMID 36385095, 2022). "Therefore, we speculated that RasGRP1 may inhibit the development of liver cancer by inhibiting EGFR-SOS1-Ras-ERK signalling pathway activation to suppress the tumour-promoting effect of IL-6 during the acute inflammatory response." (PMID 36385095, 2022).
Obesity (2 papers, 2011 to 2018). Accumulation of substantial excess body fat. "Notable among them are LINC01128 enriched with regulatory elements, RAS Guanyl Nucleotide-releasing Protein (RASGRP1) associated with high fat diet induced obesity enhancing adipocytes and lymphaniogenesis which could be plausible drivers for unhealthy fat depositions inside the body." (PMID 30671081, 2018). "Other universal genes previously shown to be increased during the expansion of the β-cell during obesity or pregnancy such as Birc5, Igf1r and Rasgrp1 also failed to increase in PPARγ deficient ob/ob islets (POKO vs. WT) further suggesting an inability of POKO islets to proliferate at a young age." (PMID 22208362, 2011).
Parkinson disease (2 papers, 2023 to 2024). A progressive degenerative disorder of the central nervous system characterized by loss of dopamine producing neurons in the substantia nigra and the presence of Lewy bodies in the substantia nigra and locus coeruleus. "Rhes and RasGRP1 facilitate the development of L-DOPA-induced dyskinesia (LID) through the involvement of mammalian target of rapamycin (mTOR) signaling in a pre-clinical model of Parkinson's disease (PD)." (PMID 38589732, 2024).
schizophrenia (2 papers, 2022 to 2023). A major psychotic disorder characterized by abnormalities in the perception or expression of reality. "The dysregulation of RasGRP1 is known to contribute to numerous disorders that range from autoimmune and inflammatory diseases and schizophrenia to neoplasia." (PMID 36675167, 2023).
T-cell leukemia (2 papers, 2013 to 2023). A malignant disease of the T-lymphocytes in the bone marrow, thymus, and/or blood. "Elevated RasGRP1 mRNA expression has been reported in T cell leukemia microarray studies and is found frequently in pediatric T cell leukemia in which it stimulates the growth of this blood cancer." (PMID 23908768, 2013).
thymic lymphomas (2 papers, 2013 to 2023). "The knockout of RasGRP1 negative regulators has also been shown to be oncogenic; specifically, DGKα−/− DGKζ−/− double knockout mice develop thymic lymphoma due to the failure to prevent the overactivation of RasGRP1 and Ras." (PMID 36675167, 2023). "Furthermore, the dysregulation of RasGRP1 in mice and cell lines has been shown to lead to the development of thymic lymphomas and T cell leukemias." (PMID 36675167, 2023).
acute lymphoblastic leukemia (1 paper, 2023). Leukemia with an acute onset, characterized by the presence of lymphoblasts in the bone marrow and the peripheral blood. "However, studies have found RasGRP1 to be overexpressed in nearly half of all T cell acute lymphoblastic leukemias (T-ALL)." (PMID 36675167, 2023).
Alzheimer disease (1 paper, 2025). A progressive, neurodegenerative disease characterized by loss of function and death of nerve cells in several areas of the brain leading to loss of cognitive function such as memory and language. "Specifically, RASGRP1, PRKCB, and NFATC1 are implicated in both RA and Alzheimer’s disease, suggesting therapeutic convergence." (PMID 40839671, 2025). "RASGRP1 and PRKCB displayed elevated expression in brain tissue, suggesting a genetic connection between RA and neuroinflammatory diseases such as Alzheimer’s disease." (PMID 40839671, 2025). "In addition to their role in RA, certain novel targets, such as RASGRP1 and PRKCB exhibit high expression in brain tissues, implicating them in neuroinflammatory processes and suggesting genetic overlap between RA and Alzheimer’s disease." (PMID 40839671, 2025). "Notably, RASGRP1 and PRKCB exhibit elevated expression in brain cells, a finding that aligns with their identification as novel biomarkers for Alzheimer’s disease." (PMID 40839671, 2025).
Burkitt lymphoma (1 paper, 2018). A rare form of malignant mature B-cell non-Hodgkin lymphoma. "As controls we included the human Burkitt lymphoma cell line Ramos and the T cell line Jurkat (which were previously shown to express RasGRP3 and RasGRP1, respectively)." (PMID 29523808, 2018).
celiac disease (1 paper, 2011). An autoimmune genetic disorder with an unknown pattern of inheritance that primarily affects the digestive tract. "Lastly, four of the nine TPOA associated SNPs (in SH2B3, CTLA4, BACH2 and UBASH3A) have also been associated with celiac disease (but not the SNPs in RASGRP1, STAT4, PTPN22, IL2 and FCRL3)." (PMID 21829393, 2011).
Dyskinesia (1 paper, 2020). A movement disorder which consists of effects including diminished voluntary movements and the presence of involuntary movements. "In a PD-mouse model, l-DOPA induces dyskinesia by increasing the Ras GEF RasGRP1 protein levels." (PMID 32878220, 2020). "Moreover, as previously explained, simultaneous signaling by the RasGRP1/Rheb/mTORC1 and RasGRP1/H-Ras/ERK axes could underlie the dyskinesia suffered by PD patients who have been treated with L-DOPA for a prolonged time." (PMID 32878220, 2020). "In contrast, l-DOPA-treated RasGRP1-/- mice do not display dyskinesia." (PMID 32878220, 2020).
endometrial cancer (1 paper, 2019). Primary or metastatic malignant neoplasm involving the endometrium (mucous membrane that lines the endometrial cavity). "Six HiChIP target genes (BRAP, RASGRP1, HOXB1, HOXB6, HOXB7 and HOXB8) were enriched for miRNA targets of MIR196A1, itself a HiChIP target gene, providing evidence to link these genes together in a potential network that may mediate the effects of endometrial cancer risk variation." (PMID 31561579, 2019).
heart failure (1 paper, 2024). Inability of the heart to pump blood at an adequate rate to meet tissue metabolic requirements. "Functionally, in myocardial tissue, RASGRP1 mediates angiotensin П-induced phosphorylation of p38 MAPK and expression of periostin protein, inhibiting the expression of RASGRP1 in the heart may help improve heart failure." (PMID 38730425, 2024). "Inhibiting the expression of RASGRP1 may contribute to the improvement in heart failure." (PMID 38730425, 2024).
Hyperglycemia (1 paper, 2024). An increased concentration of glucose in the blood. "Previous studies have shown that compared with non-diabetic or normal blood glucose group, diabetic or hyperglycemia group had lower RASGRP1 expression level, while RASGRP1 expression level was negatively correlated with HbA1c." (PMID 38730425, 2024).
IgA Nephropathy (1 paper, 2016). "In conclusion, we observed novel associations of RGS1 and RASGRP1 variants in IgA Nephropathy." (PMID 27804980, 2016). "In the current study, we observed novel associations between RASGRP1 variants in IgA Nephropathy." (PMID 27804980, 2016). "We observed novel associations of RGS1 and RASGRP1 variants in IgA Nephropathy." (PMID 27804980, 2016).